SLC2A3 (solute carrier family 2 member 3)
Diseases named in the same sentence as SLC2A3 in open-access papers (continued):
Sharing a sentence is not in itself a finding about the gene and the disease.
cancer (203 papers, 2008 to 2026). A tumor composed of atypical neoplastic, often pleomorphic cells that invade other tissues. "HIF-1 induces the expression of solute carrier family 2 member 1 (SLC2A1) and solute carrier family 2 member 3 (SLC2A3), which encode GLUT1 and GLUT3, respectively, to promote glucose uptake to meet the demand of glucose for the growth of hypoxic cancer cells." (PMID 39858016, 2025). "For example, elevated SLC2A1 (GLUT1) and SLC2A3 (GLUT3) have been associated with increased cancer metabolism." (PMID 35755805, 2022). "Solute carrier family 2(facilitated glucose transporter), member 3 (SLC2A3) encodes glucose transporter 3 (GLUT3), which can inhibit ferroptosis and is closely related to the poor prognosis of cancer." (PMID 35281840, 2022). "HIF-1 induces the expression of solute carrier family 2 member 1 (SLC2A1) and solute carrier family 2 member 3 (SLC2A3), which encode GLUT1 and GLUT3 respectively, to promote glucose uptake to meet the insatiable demand of glucose for growth of hypoxic cancer cells." (PMID 34359884, 2021). "These target genes, including IGFBP1, WNT1, WNT10B, TGFB1, PCK1, and SLC2A3, are critical for cancer cell proliferation and metastasis." (PMID 42311859, 2026). "SLC2A3 exhibited a positive correlation with immune checkpoint genes (ICGs) across the majority of cancers, whereas an opposite trend was observed in TGCT." (PMID 41268544, 2025). "In this study, we comprehensively analyzed SLC2A3 expression across multiple cancer types and evaluated its potential prognostic significance." (PMID 41268544, 2025). "For example, elevated SLC2A1 (GLUT1) and SLC2A3 (GLUT3), which facilitate the transport of glucose across the plasmatic membrane, have been associated with increased cancer metabolism." (PMID 40141095, 2025). "Collectively, our data imply that SLC2A3 serves as an oncogenic driver in multiple cancers, contributing to KIRC progression via the enhancement of pro-tumorigenic pathways." (PMID 41268544, 2025). "In contrast to SLC2A1 and SLC2A3, SLC5A2 is a concentrative transporter and thus has a greater efficiency than SLC2A1/SLC2A3 in transporting glucose into cancer cells." (PMID 38339256, 2024). "In cancer cells, the elevated expression of SLC2A3 helps to meet the increased glycolysis requirements and promotes the Warburg effect." (PMID 37621680, 2023). "The high or specific expression of other glucose transporters such as GLUT2/SLC2A2, GLUT3/SLC2A3, GLUT12/SLC2A12 and the fructose transporter GLUT5/SLC2A5 has also been associated with various cancer types and specific cancer stages." (PMID 36770817, 2023). "There is a growing body of literature that focusing on the upregulating of SLC2A3 to research cancer diagnosis and therapy." (PMID 36247875, 2022). "With the deep interrogation of glycolysis-related gene SLC2A3 in diverse cancer types, there is a pressing need to research the correlation between SLC2A3 and immune infiltration." (PMID 36247875, 2022). "SLC2A3 is a ferroptosis marker involved in transmembrane glucose transport, and current studies on SLC2A3 have focused on cancer." (PMID 36686646, 2022). "We also analyzed the expression of SLC2A3 in different organs and pan-carcinomas using the TCGA database." (PMID 35957685, 2022). "In these cell lines, it was also shown that the use of glucose transport inhibitors that interact with SLC2A3 and related molecules can sensitize cancer cells to drugs including DNR under hypoxic conditions." (PMID 32429253, 2020). "This study was designed to identify mechanisms mediating the cancer-promoting effects of SLC2A3 in GC, with focus on its glycolysis reprogramming function, and to reveal molecular links between SLC2A3 and immune regulation." (PMID 33061855, 2020). "Some DNA-damaging anticancer agents including adriamycin, camptothecin and etoposide were reported to induce cancer cell death by reducing SLC2A3 expression in HeLa cells." (PMID 33061855, 2020).
cancer (continued). "A slight increase of IFI27, FOXQ1, PRF1, and SLC2A3 genes in CSCs probably implicate in phenotypes of cancer stem cells that were often quiescent, but being able to exhibit their chemoresistant properties." (PMID 32592372, 2020). "Recent studies have revealed that SLC2A3 acts as a transporter with a high affinity for glucose and a high calculated glucose turnover rate in several malignant tumor tissues, including GC." (PMID 33061855, 2020). "We found that the mRNA levels of both SLC2A1 and SLC2A3 were significantly upregulated in cancer tissues of these CRC patients." (PMID 32873793, 2020). "The RNA-seq data of multiple malignancies in TCGA showed that SLC2A3 expression differed in cancer and corresponding normal tissues in a variety of cancers." (PMID 33061855, 2020). "Mean SLC2A3 gene expression was significantly higher in more disseminated invasion type cancers (p = 0.0001)." (PMID 25412955, 2015). "SLC2A3, also named as glucose transporter 3 (GLUT3), has a high affinity for glucose, and is recognized as an oncogene in several human cancers." (PMID 24124917, 2013). "We conducted a comprehensive pan-cancer analysis of SLC2A3 using publicly available datasets." (PMID 41268544, 2025). "For ENHss, SLC2A3 expression correlated positively in seven cancers but negatively in twelve." (PMID 41268544, 2025). "This study highlights a novel mechanism by which SLC2A3 may raise the chaos of the microenvironment to facilitate cancer progression, paving the way for further research." (PMID 38778609, 2025). "SLC2A3 expression is broadly positively correlated with immune checkpoints, modulators, and several immune cells in most cancers, but shows a negative association in TGCT." (PMID 41268544, 2025). "In the current study, we computed SLC2A3, a cancer promoter that may aggravate TME dysregulation, especially the negative correlation with CD8+T cells." (PMID 38778609, 2025). "Overexpression of SLC2A3 has been shown to promote cell survival and growth in cancer." (PMID 40110037, 2025). "For a long time, it was thought that only SLC2A1 is responsible for the increased influx of glucose into cancer cells and that SLC2A3 may contribute to glucose uptake in cancer cells to some extent." (PMID 38339256, 2024). "In our results, the up-and-down-regulatory functional experiments revealed that SLC2A3 could comprehensively underpin the cancer-promoting aspects in both vivo and vitro, providing a preliminary basis for its cancer-facilitating properties." (PMID 38625978, 2024). "Further exploration of the interaction between SLC2A3 up-regulated cancer cells and immune cells is of major importance and may provide new insights for cancer immunotherapy." (PMID 37621680, 2023). "SLC2A3 was mainly related to cancer stage development and short OS in HNSCC patients." (PMID 37542344, 2023). "Thus, According to the mediation in glucose transport, SLC2A3 was regarded as a cancer-promoting gene." (PMID 36247875, 2022). "The prognostic role of SLC2A3 in cancers has recently gained attention." (PMID 36247875, 2022). "SLC2A3 is upregulated in various cancer types and promotes proliferation, invasion, and metabolism." (PMID 36247875, 2022). "As for risk gene SLC2A3, the expression had a positive correlation with drug sensitivity of cancer cells to Trametinib, but showed a negative correlation with drug sensitivity of cancer cells to Palbociclib and Carfilzomib." (PMID 34745224, 2021). "SLC2A3 (also known as GLUT3) encodes the glucose transporter (GLUT) protein which influences the processes of energy metabolism and is related to poor prognosis in various cancers." (PMID 33926457, 2021). "To further explore the mechanisms underlying the stimulatory effects of SLC2A3 on glycolysis promotion, we analyzed key signaling pathways that could be influenced in SLC2A3 activated cancer cells." (PMID 33061855, 2020). "The roles of SLC2A14 and SLC2A3 in cancer have more recently gained attention." (PMID 32580154, 2020).
cancer (continued). "Including GC, positive staining results for SLC2A3 have been detected in several malignant tumor tissues, suggesting that SLC2A3 may participate in facilitating glucose uptake in the tumors with intense glucose requirements." (PMID 29867504, 2018). "The role of SLC2A1/GLUT1 and SLC2A3/ GLUT3 has been widely studied in cancers." (PMID 29876008, 2018). "18FDG-PET imaging is useful when cancers express high levels of SLC2A1 or SLC2A3." (PMID 28978124, 2017). "However, the results showed that more advanced tumors (pT3-4, pN1-3) were more likely to be more frequently positive and to have a higher mean levels for both SLC2A1 and SLC2A3 transcripts than less advanced cancers (pT1-2, N0)." (PMID 25412955, 2015). "SLC2A3 (also known as GLUT3) is a glucose transporter protein that may be important for cellular metabolism in some cancers." (PMID 21326611, 2011). "CIBERSORT analysis showed that SLC2A3 expression was positively associated with CD4 memory-activated T cells, M0 macrophages, activated mast cells, and neutrophils, but negatively correlated with regulatory T cells (Tregs), activated NK cells, and memory B cells in most cancers." (PMID 41268544, 2025). "In addition to the role of SLC2A3 in stem traits of BCa, targeting SLC2A3 may enhance effective cancer treatment." (PMID 36902193, 2023). "Targeting SLC2A3 may facilitate effective cancer management." (PMID 36902193, 2023). "Importantly, improvement in inhibitor’s efficacy (IC50), selectivity of the target, and identification of therapeutic windows while taking cancers’ specific genotype and phenotype into account, are needed for SLC2A3 inhibitors to become effective anti-cancer therapeutics." (PMID 33061855, 2020). "The prognostic predictive potential of SLC2A3 for HNSCC has been reported, and this molecule also mediates cancer cell proliferation and, migration, and immune responses." (PMID 38409358, 2024). "Cancer cells often overexpress glucose transporters such as SLC2A1/GLUT1 and SLC2A3/GLUT3 to take in large amounts of extracellular glucose to support their high rates of proliferation." (PMID 39406918, 2024). "To understand the mechanisms associated with the selected four SLCs, we performed GSEA to identify pathways enriched in cancers with high expression of SLC16A3, SLC53A1, SLC25A32, and SLC2A3." (PMID 39335197, 2024). "Besides, SLC2A3 may serve as a promising stemness target facilitating cancer effective management." (PMID 36902193, 2023). "While the correlations between the expression levels of SLC2A3 and 28 TIL types across human cancers were explored in the TISIDB database." (PMID 36247875, 2022). "However, the effect of SLC2A3 on the prognosis of patients with cancer remains unclear." (PMID 35957685, 2022). "For a start, solute carrier family 2 member 3 (SLC2A3), asparagine, and asparagine synthetase are all remarkably expressed in PNI+ cancer." (PMID 36582785, 2022). "Expression of several genes known to be involved in cancer progression were identified by this method, including HMGA2, FHL1, SLC2A3, ADAMTS1, UPP1, and TGM2." (PMID 32054828, 2020). "Cancer cells predominantly express SLC2A1 (GLUT1) and SLC2A3 (GLUT3) to transport glucose across the cell membrane and Hexokinase 1 and Hexokinase 2 to phosphorylate glucose." (PMID 31784510, 2019). "Pair-wise tests presented significant (p < 0.05) hypo-methylated genes between Cancer/control and Family/control pairs on SEPT9 at the intron region, SLC2A1/GLUT1 at the promoter region, and SLC2A3/GLUT3 at the intron region." (PMID 29876008, 2018). "Correlation analysis indicated a positive association between SLC2A3 expression and TMB across eight cancer types, while a negative correlation was observed in LIHC." (PMID 41268544, 2025). "In terms of HRD, elevated SLC2A3 correlated positively in six cancers, but showed negative correlations in GBM and STAD." (PMID 41268544, 2025).
cancer (continued). "Therefore, the reliability of a PET scan with 18FDG as the probe in cancer detection still depends solely on SLC2A1 (and SLC2A3)." (PMID 38339256, 2024). "The induction of GLUT transporters (SLC2A1/GLUT1 and SLC2A3) to support aerobic glycolysis (the Warburg effect) is well established, a phenomenon that is reinforced by HIF-1/2α transcriptional control in the hypoxic niche of malignant tumors." (PMID 38414005, 2024). "In brief, DUSP1, ZFP36, SLC2A3, HMGB1, STAT3, MT3, and ALOX5 were all FRGs that might be involved in cancer development and immune regulation." (PMID 36131791, 2022). "Other studies have shown that SLC2A3 was directly related to SOX9, TRIM66, and HMGA1, which could promote cancer cell proliferation, migration, and invasion." (PMID 36247875, 2022). "Indeed, certain cancer cells upregulate the gene expression of the glucose transporters GLUT1 (SLC2A1) and GLUT3 (SLC2A3) to increase glucose uptake, which correlates with poor prognosis." (PMID 31288376, 2019). "However, our data highlight that the functional implications of SLC2A3 are not entirely uniform across cancers." (PMID 41268544, 2025). "Interestingly, contrary to the trend that SLC2A3 expression is positively correlated with TMB in most cancers, a negative correlation was observed in LIHC." (PMID 41268544, 2025). "According to existing studies, it is found that SLC2A3 has a high affinity for glucose, which can ensure the effective uptake of glucose by cells, and the low expression of KMT2D significantly affects the effect of SLC2A3, thereby inhibiting cancer cells’ uptake and utilization of glucose." (PMID 35281840, 2022). "Therefore, we believe that high expression of YTHDF1 may promote the expression of SLC2A3, promote the glycolysis of ESCA, and finally promote the progress of cancer." (PMID 35401696, 2022). "The relationship between SLC2A3 and immune infiltration in human cancers is not widely studied." (PMID 36247875, 2022). "Additionally, the expression of SLC2A3, a key glucose transporter in glycolysis, was markedly increased, indicating that UBD overexpression may facilitate glycolytic metabolism by enhancing glucose uptake in cancer cells." (PMID 40692714, 2025). "The mRNA levels of three out of six genes we tested (SLC2A3, GPI, and PDK3) were selectively decreased by PRDX2 and PRDX4 during prolonged hypoxia, suggesting that PRDX2 and PRDX4 may be negative regulators of glucose reprogramming in cancer cells exposed to prolonged hypoxia." (PMID 26837221, 2016). "Notably, the sensitivity of 18FDG-PET for HCC is lower than for other malignant cancers, which suggests 18FDG (−) HCC does not overexpress SLC2A1 and SLC2A3." (PMID 28978124, 2017).
infection (22 papers, 2007 to 2025). The state of being infected such as from the introduction of a foreign agent such as serum, vaccine, antigenic substance or organism. "As glucose is the substrate of glycolysis, and expression of the genes encoding GLUT-1 (SLC2A1) and GLUT-3 (SLC2A3) were significantly increased after infection, we hypothesized that glucose uptake may also be enhanced." (PMID 35693822, 2022). "Our improved method of CNV allele calling should permit future exploration of whether SLC2A3 CNVs have an impact on other immune phenotypes such as susceptibility to infection." (PMID 30997344, 2019). "We found that both pathways were comparably induced during first and second infection with one notable exception: monocytes switched from upregulating the glucose transporter Slc2a1 in first infection to Slc2a3 in second infection." (PMID 33752799, 2021). "Similar observations have been made using Caco-2 epithelial cells, where HIF-induced genes including NOS2, ANKRD37, GADD45A, ITF, MIR210HG, and SLC2A3 are also upregulated in Giardia-exposed cells, suggesting that IECs respond to increased oxidative stress upon infection." (PMID 37375100, 2023). "In neonates, suffering from infection an increased expression of GLUT3 (SLC2A3) was observed." (PMID 37762476, 2023). "The reduced expression of GLUT3 associated with genetic deletion of SLC2A3 could offer some level of protection to the host from infection with Chlamydia bacteria and blood-stage parasites that rely on GLUT3 from their host cells for glucose metabolism." (PMID 30997344, 2019). "Induced pluripotent stem cell-derived cardiomyocytes (iPSC-CMs) also show significant enrichment for hypoxia-related genes upon infection with T. cruzi, including HIF-1α, VEGFB, HK2, SLC2A3, ENO1, and LDHA." (PMID 37375100, 2023). "Many solute carrier (SLC) family genes were also activated at 24 or 48 h after infection, including SLC16A12, SLC2A3, SLC16A6, and SLC32A1." (PMID 37211158, 2023).
psychiatric disorder (1 paper, 2019). A disorder characterized by behavioral and/or psychological abnormalities, often accompanied by physical symptoms. "In a study of copy number variations in psychiatric disorders focusing on ADHD, patients were found to have an additional copy of the SLC2A3 region." (PMID 31507372, 2019).
SLC2A3 also shares sentences with these, for which no sentence is quoted: brain tumor (11 papers); lung adenocarcinoma (10); Cognitive impairment (9); hepatocellular carcinoma (9); gestational diabetes (7); triple-negative breast carcinoma (7); acute myeloid leukemia (5); metastatic colorectal cancer (4); osteosarcoma (4); pancreatic cancer (4); astrocytoma (3); dyslexia (3); type 2 diabetes (3); adenocarcinoma (2); Anxiety (2); autism spectrum disorder (2); bacterial infection (2); Chlamydia infection (2); chronic obstructive pulmonary disease (2); colon adenocarcinoma (2); depression (2); diabetic retinopathy (2); epilepsy (2); Glucose intolerance (2); heart failure (2); Hepatic steatosis (2); Hypoinsulinemia (2); invasive ductal breast carcinoma (2); meningioma (2); metabolic disease (2).
A further 96 diseases each share a sentence with SLC2A3 in 2 papers or fewer.